FAF1 (Fas associated factor 1)
Diseases named in the same sentence as FAF1 in open-access papers (continued):
Sharing a sentence is not in itself a finding about the gene and the disease.
lung adenocarcinoma (1 paper, 2023). A carcinoma that arises from the lung and is characterized by the presence of malignant glandular epithelial cells. "Furthermore, the downregulation of FAF1 significantly inhibited cell viability and tended to promote early apoptosis in a lung adenocarcinoma cell line." (PMID 37999107, 2023). "In this study, FAF1 downregulation in the lung adenocarcinoma cell line A549 promoted early apoptosis, whereas no conclusion could be reached when FAF1 was upregulated in the lung large-cell carcinoma cell line H460." (PMID 37999107, 2023).
lung carcinoma (1 paper, 2023). "The downregulation and mutation of FAF1 have been reported in a variety of human tumors, but there have been few studies on lung cancer." (PMID 37999107, 2023). "In lung cancer cell lines, FAF1 downregulation hindered cell viability and tended to promote early apoptosis." (PMID 37999107, 2023). "FAF1 expression was examined in NSCLC specimens as well as human lung cancer cell lines." (PMID 37999107, 2023). "We do not know why these associations occurred in lung cancer, and no information about the interaction of FAF1 and EGFR has been reported thus far." (PMID 37999107, 2023). "In addition, changes in cell viability and apoptosis upon regulating FAF1 expression were investigated in lung cancer cell lines." (PMID 37999107, 2023). "The downregulation of FAF1 mRNA has also been reported in gastric cancer and lung cancer." (PMID 37999107, 2023). "Furthermore, 408 of 609 lung cancer specimens (67.0%) had positive FAF1 expression." (PMID 37999107, 2023). "A549 cells demonstrated higher mRNA expression of FAF1 than NHBE cells, as well as other human lung cancer cells (PC9, H1299, and H460)." (PMID 37999107, 2023). "We investigated FAF1 protein expression in NSCLC and how it affects lung cancer cell viability and apoptosis progression in vitro." (PMID 37999107, 2023). "Thus, in vitro recapitulation of the tumorigenic role of FAF1 may be insufficient when considering a variety of lung cancer cells, for example, with or without EGFR mutation." (PMID 37999107, 2023). "The FAF1 protein was found in the human lung cancer cell lines A549, PC9, and H1299, as well as the normal human bronchial epithelial cell line NHBE, but not in the human lung cancer cell line H460." (PMID 37999107, 2023).
lymph node metastasis (1 paper, 2023). "In our cohort, the expression of FAF1 was statistically higher in patients with an advanced pathological stage, an advanced extension of primary tumor size, and subsets with worse lymph node metastasis, respectively." (PMID 37999107, 2023).
mental retardation (1 paper, 2013). "Interestingly, mutation of the Whsc2 gene is associated with mental retardation and Faf1 is a Fas-related regulator of apoptosis." (PMID 23762244, 2013).
myeloma (1 paper, 2013). "For example, BIRC2 and FAF1 are among the top 10 genes identified using DR-Integrator analysis of a paired copy number and gene expression dataset for myeloma." (PMID 23418540, 2013).
neuroblastoma (1 paper, 2020). Neuroblastoma (NB) is the most common solid, extracranial childhood tumor. "This study aimed to determine whether FAF1 is also secreted at the cellular level and investigate FAF1 secretion in SH-SY5Y human neuroblastoma cells." (PMID 32831099, 2020).
oropharyngeal carcinoma (1 paper, 2025). Carcinoma, predominantly squamous cell, arising from the epithelial cells of the oropharynx. "In oropharyngeal carcinomas it has been shown that FAF1 gene expression is associated with the occurrence of locoregional recurrence." (PMID 41357812, 2025).
parasite infection (1 paper, 2021). "Thus, the change of host FAF1 protein and mRNA levels after T. gondii stimulation were measured to investigate whether FAF1 is associated with the process of parasite infection." (PMID 34464509, 2021).
retinal ischemia (1 paper, 2018). A ischemic disease that involves the retina. "Given that FAF1 functions as a key regulator of JNK1-dependent necrosis upon ischemic stress in RGC5 cells, we used a mouse model of retinal ischemia to validate the role of FAF1 in ischemia-induced neurodegeneration in vivo." (PMID 30200976, 2018). "Immunoblot assay showing JNK1 activation in response to retinal ischemia in retinas of Dkk3-Cre;Faf1+/+ mice (n = 3 eyes)." (PMID 30200976, 2018). "(b) Immunoblot assay showing JNK1 activation in response to retinal ischemia in retinas of Dkk3-Cre;Faf1+/+ mice (n = 3 eyes)." (PMID 30200976, 2018). "Collectively, our data show that FAF1 mediates retinal cell death in a mouse model of retinal ischemia." (PMID 30200976, 2018). "Retinal ischemia-induced JNK1 activation was observed in Dkk3-Cre;Faf1+/+ mice but not in Dkk3-Cre;Faf1flox/flox mice." (PMID 30200976, 2018).
Stroke (1 paper, 2022). Sudden impairment of blood flow to a part of the brain due to occlusion or rupture of an artery to the brain. "Importantly, GWAS have associated variants of several of the gene targets of miR-24-3p;FAF1, GATA3, MMP14, NOS3 and PTPRF with stroke." (PMID 36613546, 2022).
tumor (29 papers, 2006 to 2025). "The role of FAF2 between ACC was the same as FAF1, and it was negatively associated with the stromal and immune score but positively associated with tumour purity." (PMID 38365777, 2024). "Faf1 encodes FAS-Associated Factor 1 (FAF1) that acts as a tumor suppressor by regulation of apoptosis and NF-κB activity, and ubiquitination and proteasomal degradation." (PMID 37414763, 2023). "Fas Associated Factor 1 (FAF1), a component of the death-inducing signalling complex, is frequently downregulated or lost in a number of human tumour types." (PMID 25496077, 2014). "Given that FAF1 has been implicated as a tumor-suppressor and we demonstrated that FAF1 inhibits SAP130-mediated transcriptional function, stability and cell proliferation-promoting ability, it is possible that FAF1 would attenuate any oncogenic potential of SAP130." (PMID 38172660, 2024). "FAF1 expression was inversely correlated with SARC, TGCT, THYM, and UCS, indicating that elevated FAF1 expression may be associated with reduced tumour purity." (PMID 38365777, 2024). "Independent of PG production, arachidonic acid could be pro-tumorigenic by stabilizing β-catenin through direct interaction with Fas-associated factor 1 (FAF1), thus stimulating tumor growth." (PMID 36970499, 2023). "Downregulation of FAF1 mRNA was associated with tumor differentiation and distant metastasis." (PMID 23304123, 2012). "As in mouse model, the loss of FAF1 may relate to aberrant NF-β signalling and tumour progression." (PMID 38365777, 2024). "Comparison of FAF1 expression with clinicopathological characteristics identified negative associations of FAF1 expression with tumor size (P = 0.024), histology grade (P < 0.01), tumor infiltration (P < 0.01), lymph node metastasis (P < 0.01), and TNM stage (P < 0.01)." (PMID 28030825, 2017). "Studies on the progression of tumours in asbestos-induced malignant mesothelioma mouse models have shown that FAF1 is an essential factor in regulating the NF-β pathway." (PMID 38365777, 2024). "Along these lines, reduced FAF1 expression was found in some human tumors, making the protein a candidate tumor suppressor." (PMID 38172660, 2024). "FAF1 expression with varying degrees of brown staining in tumor tissues was localized in both the cytoplasm and nuclei of the tumoral cells, but not in non-tumor tissues." (PMID 37999107, 2023). "FAF1 is a tumor suppressor and metastasis inhibitor whose expression is downregulated in various cancers." (PMID 32831099, 2020). "First, FAF1 plays a tumor- suppressive role through activation of the apoptotic machinery and NF-κB suppression." (PMID 32831099, 2020). "Most of all, FAF1 can serve as a tumor suppressor involving in the regulation of apoptosis and NF-kappaB activity in HeLa cells." (PMID 30915356, 2019). "H. pylori, through NF-κB induction on tumor cells, reduces the expression of FAF1, promoting cell survival, and induces the inflammatory cytokines TNF-α and IL-8, which is associated to tumor growth." (PMID 29315242, 2018). "Univariate analysis identified the following predictors of survival: FAF1 expression, tumor diameter, tumor location, tumor infiltration, histology grade, lymph node metastasis, distant metastasis and TNM stage." (PMID 28030825, 2017). "FAF1 also functions as a tumor suppressor, and ectopic FAF1 expression reduces the migration of cancer cells in vitro and invasion/metastasis in vivo." (PMID 28484086, 2017). "Filtering yielded 46 likely somatic mutations in the tumor, of which 7 (affecting EIF4A1, EPHA3, FAF1, IPO8, KIAA1377, LIMCH1, and NIPBL) were confirmed in the RNASeq results." (PMID 25861239, 2015). "Given the proapoptotic function of FAF1, downregulation would be expected to promote the survival of tumor cells as well as their resistance to anticancer therapy." (PMID 23304123, 2012). "FAF1 is a tumour suppressor gene that plays a role in various cancers." (PMID 38365777, 2024).
tumor (continued). "Thus, AKT, through FAF1 inactivation, triggers a tumour-promoting self-reinforcing cycle of the TGF-β pathway, thereby stimulating cancer cell invasion and metastasis." (PMID 38365777, 2024). "Clearly, these studies have classified FAF1 as a tumor suppressor." (PMID 37999107, 2023). "Both studies suggest FAF1 as a tumor suppressor in NSCLC, which contradicts our findings." (PMID 37999107, 2023). "Secondly, the FAF1 human orthologue of C. elegans UBXN‐3 is a candidate tumour suppressor." (PMID 34269473, 2021). "Since the human orthologue of UBXN‐3, FAF1, is a candidate tumour suppressor, these findings suggest that manipulation of CMG disassembly might be applicable to future strategies for treating human cancer." (PMID 34269473, 2021). "Immunohistochemistry of HGC-27/FAF1 tumor sections showed FAF1 to localize in the cytoplasm." (PMID 28030825, 2017). "Thus, a self-enforcing loop directing the tumour-promotive TGF-β pathway is triggered by AKT through the inactivation of FAF1, via which cancer cells are stimulated to invade and metastasize." (PMID 28443643, 2017). "As a result, we concluded that FAF1 might be an effective prognostic biomarker for those tumours." (PMID 38365777, 2024). "However, the manifestation found here demonstrated that, contrary to previous reports, FAF1 reverses its role as a tumor suppressor for unknown reasons in NSCLC." (PMID 37999107, 2023). "Whether this contributes to the observed tumor suppressive effects of FAF1 should be investigated." (PMID 28030825, 2017). "In addition, FAF1 mRNA expression showed no obvious association with tumor size, infiltration degree, lymph node metastasis or clinical stage below IV." (PMID 23304123, 2012). "Some proteins with more distant relations to the chaperone cycle (CK2, FAF1, RAF1) were still found to be contributing factors in HSP-related signaling and proteostasis processes, at the same time exhibiting involvement in tumor progression." (PMID 41369326, 2025). "FAF1, initially identified as a member of the FAS death-inducing signaling complex, is an evolutionary conserved tumor suppressor that promotes apoptosis through several mechanisms." (PMID 39334449, 2024). "Our findings suggest that FAF1 plays a variety of roles in NSCLC progression, in addition to acting as a tumor suppressor." (PMID 37999107, 2023). "These genes are localised close to known cyclin-dependent kinase inhibitors and tumour suppressors CDKN1C and CDKN2A/B, respectively, but both FAF1 and MTAP have recently been proposed to harbour tumour suppressor activity in their own right." (PMID 24548782, 2014). "We semi-quantified FAF1 expression at the protein level in NSCLC tumor and non-tumor tissue without measuring it at the RNA level." (PMID 37999107, 2023). "Pre-treatment with epidermal growth factor (EGF) at a low dose promoted the lung metastasis of 4T1 cells without significantly altering primary tumour growth under the nipple; this effect on metastasis was further promoted by FAF1 depletion." (PMID 28443643, 2017). "We thought that it furthermore illustrates that FAF1 in NSCLC does not act as a tumor suppressor." (PMID 37999107, 2023). "In addition, FAF1, the orthologues of C. elegans UBXN-3 in human, is a tumour suppressor." (PMID 34368118, 2021). "FAF1, a member of the ubiquitin regulatory X (UBX) family, potentially interacts with diverse proteins and functions as a negative and/or positive regulator in variety of biological possesses, including apoptosis, tumor growth, protein degradation and chaperone activity." (PMID 28542569, 2017). "Importantly, FAF1 phosphorylation by AURKA does not regulate FAF1 levels, but phosphorylated FAF1 triggers AURKA ubiquitylation, indicating that FAF1 loss may cause AURKA upregulation in tumor tissues." (PMID 39334449, 2024). "To assess the protein expression of FAF1 in NSCLC, we conducted IHC analysis on tumor tissues and paired non-tumor tissues from NSCLC patients." (PMID 37999107, 2023).
tumor (continued). "Upregulation of the anti-apoptotic genes BCL2L2, BAG3, and downregulation of pro-apoptotic genes DAXX, FAF1, PAK1, DFFA, ENDOG was found in reprogrammed tumours pointing to a cell cycle arrest without engagement of the apoptotic pathway." (PMID 29662623, 2018).
cancer (24 papers, 2010 to 2024). A tumor composed of atypical neoplastic, often pleomorphic cells that invade other tissues. "The FAF1 mutation identified as the likely cause for the cancer under study gives room for an explanation of the sarcomatous transformation." (PMID 25861239, 2015). "FAF1 is located at chromosome 1p32.3, where a loss of heterozygosity occurs in many cancers." (PMID 37999107, 2023). "In addition, miR-24 was found to target Fas-associated factor 1 (FAF1) by binding to its amino acid coding sequence (CDS) region to regulated apoptosis in hormone-insensitive prostate cancer or other types of cancers." (PMID 30915356, 2019). "Given the role of FAF1 in restricting TGF-β signalling activity, we investigated the possibility that loss of FAF1 might be a relevant prognostic factor in late-stage cancer." (PMID 28443643, 2017). "Notably, various FAF1 mutations have been linked to cancer development; however, a mechanistic role in maintenance of genome stability has not been demonstrated." (PMID 26842564, 2016). "Other mutations, beside FAF1, are less likely to be causative for the cancer." (PMID 25861239, 2015). "In fact, loss or downregulation of FAF1 expression has been observed in various human cancers." (PMID 23304123, 2012). "Subsequent work has revealed that the FID of FAF1 interacts with a variety of downstream targets, and functional loss of FAF1 may provide a prosurvival signal to cells in disease states such as cancer." (PMID 23304123, 2012). "We postulate that loss of FAF1 function may have far-reaching effects in cancer, although its role(s) may be context-dependent." (PMID 23304123, 2012). "As a result, the loss of FAF1 anti-cancer functions may contribute to diverse hallmarks of cancer." (PMID 27754413, 2016). "The identified point mutation in FAF1 may be pathogenetic for this cancer." (PMID 25861239, 2015). "Bioinformatics analysis revealed that Fas-associated factor 1 (FAF1) has the largest number of gene alterations in the UBXD family and has been linked to survival and cancer progression in many cancers." (PMID 38365777, 2024). "To further study the relationship between expression of SAP130 and FAF1 in clinical samples, we analyzed the cancer datasets via cBioPortal database." (PMID 38172660, 2024). "An ongoing research is expected to shed light on the role of FAF1 in signaling pathways critical for normal development and cancer." (PMID 38031027, 2023). "Disruption of the FAF1–p97 interaction due to FAF1 phosphorylation by AKT is thought to drive cancer metastasis." (PMID 28819009, 2017). "Oncomine17 expression analysis revealed FAF1 downregulation in multiple human cancers in which TGF-β is pro-metastatic." (PMID 28443643, 2017). "Interaction of FAF1 with HSP70, a well-known anti-apoptotic protein and a poor prognostic factor, is another anti-cancer mechanism of FAF1." (PMID 27754413, 2016). "The significant anti-cancer functions of FAF1 were further verified when studies reported the down-regulation of FAF1 in tumors." (PMID 27754413, 2016). "FAF1 itself also has emerging roles in other cell-cycle pathways and displays altered expression levels in various cancer cell lines." (PMID 24619421, 2014). "These roles of p97-FAF1 complex and FAF1 itself make them potential therapeutic targets for the treatment of cancer and neurodegenerative disorders." (PMID 24619421, 2014). "FAF1 is a Fas-binding protein that negatively regulates capsaicin-induced apoptosis of cancer cells." (PMID 23304123, 2012). "Conversely, the FAF1 mRNA expression level was higher in well-differentiated cancer tissue than in poorly differentiated cancer tissue (0.39 ± 0.06 versus 0.19 ± 0.06, t = 9.966, P < 0.001)." (PMID 23304123, 2012). "FAF1 mRNA expression was higher in well-differentiated cancer than in poorly-differentiated cancer (0.39 ± 0.06 versus 0.19 ± 0.06, t = 9.966, P < 0.01)." (PMID 23304123, 2012).